EXOSC6 (exosome component 6)
Description:
Non-catalytic component of the RNA exosome complex which has 3'->5' exoribonuclease activity and participates in a multitude of cellular RNA processing and degradation events. In the nucleus, the RNA exosome complex is involved in proper maturation of stable RNA species such as rRNA, snRNA and snoRNA, in the elimination of RNA processing by-products and non-coding 'pervasive' transcripts, such as antisense RNA species and promoter-upstream transcripts (PROMPTs), and of mRNAs with processing defects, thereby limiting or excluding their export to the cytoplasm. The RNA exosome may be involved in Ig class switch recombination (CSR) and/or Ig variable region somatic hypermutation (SHM) by targeting AICDA deamination activity to transcribed dsDNA substrates. In the cytoplasm, the RNA exosome complex is involved in general mRNA turnover and specifically degrades inherently unstable mRNAs containing AU-rich elements (AREs) within their 3' untranslated regions, and in RNA surveillance pathways, preventing translation of aberrant mRNAs. It seems to be involved in degradation of histone mRNA. The catalytic inactive RNA exosome core complex of 9 subunits (Exo-9) is proposed to play a pivotal role in the binding and presentation of RNA for ribonucleolysis, and to serve as a scaffold for the association with catalytic subunits and accessory proteins or complexes.
Synonyms: MTR3; hMtr3p; Mtr3p; EAP4; p11
Tractability: Small molecule: a structure with a bound ligand is known. PROTAC: ubiquitination databases record sites on it; its protein half-life has been measured.
Gene: Protein-coding gene on chromosome 16 (70,246,778 to 70,251,940, reverse strand). Ensembl gene ENSG00000223496.
Subcellular location: Cytoplasm; Nucleus, nucleolus; Nucleus
Pathways (Reactome):
Metabolism of RNA: Butyrate Response Factor 1 (BRF1) binds and destabilizes mRNA; KSRP (KHSRP) binds and destabilizes mRNA; Major pathway of rRNA processing in the nucleolus and cytosol; Nuclear RNA decay; Tristetraprolin (TTP, ZFP36) binds and destabilizes mRNA; mRNA decay by 3' to 5' exoribonuclease
Cellular responses to stimuli: ATF4 activates genes in response to endoplasmic reticulum stress
Gene Ontology:
Molecular function: RNA binding; RNA exonuclease activity
Biological process: DNA deamination; RNA catabolic process; RNA processing; isotype switching; nuclear mRNA surveillance; poly(A)-dependent snoRNA 3'-end processing; rRNA catabolic process; U4 snRNA 3'-end processing; DNA metabolic process
Cellular component: cytosol; exosome (RNase complex); nucleolus; nucleus; cytoplasmic exosome (RNase complex); nuclear exosome (RNase complex); nucleolar exosome (RNase complex); nucleoplasm; catalytic complex; cytoplasm
Genetic constraint (gnomAD): Loss-of-function variants: 2 observed, 0.62 expected, observed/expected ratio (o/e) 3.23. That is too few expected variants to judge how well the gene tolerates losing a copy. Missense variants: 18 observed, 7.98 expected, observed/expected ratio (o/e) 2.26. Synonymous variants: 9 observed, 5.01 expected, observed/expected ratio (o/e) 1.79, 90% interval 0.97 to 1.96.
Homologues: Orthologues: chimpanzee EXOSC6 (99% identical), dog EXOSC6 (95% identical), pig EXOSC6 (93% identical), rat Exosc6 (92% identical), mouse Exosc6 (92% identical), guinea pig EXOSC6 (83% identical), tropical clawed frog exosc6 (56% identical), zebrafish exosc6 (46% identical), Drosophila melanogaster Mtr3 (26% identical). Paralogues in human: EXOSC4 (25% identical), EXOSC5 (25% identical).
Diseases named in the same sentence as EXOSC6 in open-access papers:
EXOSC6 is named in the same sentence as 4 diseases in open-access papers, as found by Europe PMC text mining. Sharing a sentence is not in itself a finding about the gene and the disease. The quoted sentences say what the papers report.
breast carcinoma (1 paper, 2023). "Exosome Component 6 (EXOSC6) derived from intracellular proteins has either well-defined or putative roles in breast cancer development and progression." (PMID 37087456, 2023).
colon adenocarcinoma (1 paper, 2022). "Various potential biomarkers for colon adenocarcinoma initiation and progression and drug targets were identified and discussed, including seven novel markers: ACSL4, ANK2, AMER3, EXOSC1, EXOSC6, GCLM, and TFRC." (PMID 35842572, 2022).
EXOSC6 also shares sentences with these, for which no sentence is quoted: cancer (1 paper); vacuolar myopathy (1).